CRP (C-reactive protein)
Diseases named in the same sentence as CRP in open-access papers (continued):
Sharing a sentence is not in itself a finding about the gene and the disease.
diabetes (continued). "Cardiometabolic risk factors independently associated with diabetes were: older age, higher BMI, family history of diabetes, metabolic syndrome, higher CRP and triglyceride level; whereas an independent predictor of diabetes was previous BMI." (PMID 35509100, 2022). "In univariate analysis, critical illness was significantly associated with older age, diabetes, CKD and CVD, with lower LN ratio, albumin and eGFR, and with high RDW, CRP, LDH, D-Dimer, and direct bilirubin." (PMID 35223916, 2022). "Our results agree with previous studies conducted on SLE populations that reported a correlation between CRP levels and lipid profile alterations, diabetes, obesity, and BMI." (PMID 35407457, 2022). "Diabetes, albumin, C-reactive protein, and Kt/V were important indicators of clinical outcomes in HD patients; however, these parameters were not correlated with levels of nAb production in our study." (PMID 35055386, 2022). "These preclinical findings were supported by a study in which ginger reduced TNF-α and hs-C-reactive protein (CRP) levels in patients with diabetes." (PMID 36118773, 2022). "Conclusions: this study showed that diabetes can be associated with a periodontal disease severity classification using the combination of ABL and hs-CRP." (PMID 35805792, 2022). "There have been studies suggesting that sumac reduces elevated C-reactive protein levels in diabetes, cancer, and atherosclerosis." (PMID 36505757, 2022). "Covariates included age, body mass index (BMI), race, sex, maximum C-reactive protein value, maximum D-dimer value, and comorbid diabetes mellitus." (PMID 35371748, 2022). "As expected, the prevalence of chronic health conditions increased with age, with a few exceptions including diabetes (self-reported and clinical), depression, and self-reported pain, and high CRP." (PMID 35217868, 2022). "Baseline characteristics were similar between groups of subjects stratified by absolute increase in 25(OH)D ≥ 7.5 ng/mL between day 0 and 3 and then sex for SAPS II, C-reactive protein, baseline 25(OH)D, body mass index (BMI), diabetes and ICU type." (PMID 35323650, 2022). "Presumably, due to the age difference, the ESTHER study participants were less physically active, had more frequently HDL levels <40 mg/dL, CRP ≥3 mg/L, and had a higher prevalence of depression, hypertension, diabetes, and CHD." (PMID 35624487, 2022). "Higher Gensini score are associated with an increase in S-LDL concentration and LDL size employing regression analysis, after adjusting for gender, age, diabetes, BMI, HbA1c, hs-CRP, ALT, and serum creatinine." (PMID 35209166, 2022). "In logistic regression analysis diabetes mellitus, CRP, leucocyte count, neutrophile count, NLR, TLR, LDH, SOFA and qSOFA were analysed." (PMID 35468761, 2022). "The significant positive correlation of hs-CRP with CD63 elucidates the vicious cycle of diabetes leading to inflammation and vice versa." (PMID 35710773, 2022). "There is an association between arterial stiffness and inflammation measured as C-reactive protein (CRP) levels in healthy individuals and middle-aged and elderly subjects, as well as patients with diabetes." (PMID 35268272, 2022). "Multiple studies have identified links between diabetes and inflammatory markers, such as tumor necrosis factor-α, interleukin-6, and C-reactive protein." (PMID 35971094, 2022). "We found a weak correlation between α1-3,4 fucosylation and CRP levels (correlation coefficient r = 0.29, P < 2.2 × 10−16) within the unselected sample cohort of young-adult onset diabetes." (PMID 34939081, 2022). "There were more patients with diabetes mellitus, old age, high systolic blood pressure, high serum intact parathyroid hormone (iPTH), elevated C-reactive protein, and high OPN levels in the AS group compared with the control group in hypertensive participants." (PMID 35010737, 2022).
diabetes (continued). "Among the clinical and laboratory parameters evaluated, we report that elevated CRP values, neutrophil count, hyperferritinemia, diabetes, requirement of invasive mechanical ventilation and the length of hospitalization contribute to in-hospital death." (PMID 35453779, 2022). "In the multivariate Cox proportional hazards models, higher CRP levels (HR: 1005 (CI: 1001–1008), p = 0.004) and diabetes as a concomitant disease (HR: 2116 (CI: 1119–4002), p = 0.02) were associated with higher probability of ICU admission." (PMID 35566412, 2022). "C-reactive protein, right coronary CTO and diabetes mellitus were independent risk factors for poor coronary collateral circulation." (PMID 36386339, 2022). "The risk factors for IAA involve factors relating to poorer immune functioning (i.e., diabetes mellitus) and more profound infection (i.e., high c-reactive protein (CRP))." (PMID 35911350, 2022). "When comparing the S- and L- groups, mortality before 12 months was statistically significantly associated with older age, ASA scores greater than 2, higher CA 19-9 and CRP levels, the presence of diabetes mellitus, and active smoking." (PMID 35939088, 2022). "In our study, the history of CKD, use of norepinephrine, presence of diabetes mellitus, serum CRP level and COVID severity index based on chest CT were the factors associated with development of AKI." (PMID 35730863, 2022). "Studies were selected if sedentary behaviour and physical activity were measured by accelerometer in the general population, and if associations were reported with glucose, insulin, HOMA-IR, insulin sensitivity, HbA1c, diabetes incidence, CRP and IL-6." (PMID 35544519, 2022). "The scoring system consisted of five variables routinely assessed for FUO patients in clinical practice: diabetes mellitus, chills, CRP, PCT, and neutrophil percentage." (PMID 36482449, 2022). "These were: older age (p < 0.001), diabetes (p < 0.001), hypertension (p < 0.001), pulmonary embolism (p = 0.015), cough (p = 0.005), high CRP (p < 0.001), high CO-RAD scale (p < 0.001), malaise (p = 0.017), dyspnea (p = 0.007) and high viral load (p < 0.001)." (PMID 36494866, 2022). "Other important features included creatinine >771 μmol/L, peripheral artery disease, smoking history, diabetes mellitus, CRP and cardiovascular disease." (PMID 36472981, 2022). "Age, BMI, AST, ALT, FBG, TG, SBP and CRP, and frequencies of hypertension and diabetes were all significantly higher in the low HGS group." (PMID 35887915, 2022). "Age, sex, educational history, body mass index, medical condition (hypertension, heart disease, diabetes mellitus),C‐reactive protein (CRP), interleukin‐6 (IL‐6) and physical activity (light, moderate–vigorous)." (PMID 34997702, 2022). "Shared significant loci across infections and non-infectious phenotypes in the UK Biobank cohort were found, suggesting associations for example between SNPs identified for abdominal infections and CRP, rheumatoid arthritis, and diabetes mellitus." (PMID 35173190, 2022). "Biochemical parameters (fasting blood sugar, glycated hemoglobin, C-reactive protein) and the duration of diabetes were recorded." (PMID 35888628, 2022). "No substantial difference was observed between the two groups in terms of BNP, CRP, lipid profiles, hypertension, diabetes, and CAD family history." (PMID 35355959, 2022). "Five independent predictors available within 24 h after admission for BSI were identified: presence of diabetes mellitus, chills, C-reactive protein level of 50–100 mg/L, procalcitonin > 0.3 ng/mL, neutrophil percentage > 75%." (PMID 36482449, 2022). "The degree of vascular endothelial injury of patients with both diabetes mellitus (DM) and coronary heart disease, has been observed to be closely related to serum adiponectin, C-reactive protein levels, and insulin resistance." (PMID 35890325, 2022).
diabetes (continued). "An inverse association of bilirubin with C-reactive protein (CRP), was also reported in various diseases as obesity and diabetes." (PMID 35327498, 2022). "In a multivariable regression model including all studied parameters, higher age, male sex, BMI ≥35 kg·m−2, diabetes, HbA1c >8.1%, CRP ≥30 mg/L and GGT >10 upper limit of normal were independently associated with an increased risk of mortality." (PMID 35646955, 2022). "For example, C-reactive protein and interleukin-6, typical inflammatory factors, were present at a high level in patients with diabetes and frailty." (PMID 36726468, 2022). "Patients with hypertension or diabetes had a higher CRP level (6.95 ± 2.89 vs. 5.27 ± 3.2 mg/L, p = 0.05; 6.83 ± 2.85 vs. 5.28 ± 3.2 mg/L, p = 0.05, respectively)." (PMID 36003285, 2022). "Women had higher cholesterol and CRP levels, but lower rates of mortality and diabetes compared to men at all time points." (PMID 36094936, 2022). "Modest drinkers were more educated, less obese, more active, less smoked, and had lower rates of hypertension, diabetes, and high triglycerides, proteinuria, high uric acid and high level of C-reactive protein when compared with regular drinkers." (PMID 35523974, 2022). "Patients with both high CRP (>33 mg/L) and high troponin (>118,000 ng/L) levels were older and had a higher prevalence of diabetes mellitus and prior heart failure compared to the rest of the cohort." (PMID 35566579, 2022). "Elevated CRP has been found to be strongly related to increased diabetes development due to the biological mechanism of low-grade chronic inflammation in glucose metabolism disorders." (PMID 36613000, 2022). "At high altitudes, the proportion of patients with coronary heart disease and diabetes was low, while dyslipidemia, homocysteine, CRP, erythrocytosis, hyperuricemia, and alcohol abuse was significantly higher." (PMID 35493834, 2022). "Among these inflammatory markers, CRP has been found to be strong and independent for both the development of incident diabetes and cardiovascular complications." (PMID 36381804, 2022). "In contrast, diabetes, atrial fibrillation, admission NIHSS, periostin level, NLR, CRP as well as creatinine levels were inversely associated with ASPECT score < 6 calculated in univariate analysis." (PMID 36010292, 2022). "CRP and increased proinflammatory cytokines interleukin 6 correlated with worse outcomes after endovascular procedure in patients with diabetes and PAD." (PMID 35450383, 2022). "Logistic regression models were constructed accounting for a set of potential confounders (age, sex, smoking, body mass index (BMI), diabetes, educational level, alcohol intake) and high sensitivity-C-reactive protein (hsCRP)." (PMID 36114562, 2022). "A new risk estimator, the Reynolds Risk Score, was developed in 2007 to include family history of premature myocardial infarction, high-sensitivity CRP, and hemoglobin A1c (for individuals with diabetes)." (PMID 36304737, 2022). "When all these factors were analyzed together, age, male sex, diabetes, CKD, oxygen saturation, and CRP, were independently associated with AKI occurrence." (PMID 35236891, 2022). "Patients with CKD who were diagnosed with PAS (68 patients, 43.3%) were older, had a higher percentage of hypertension or diabetes mellitus, higher systolic blood pressure, and higher fasting glucose, C-reactive protein, and TMAO levels." (PMID 36006188, 2022). "Mortality is significantly higher among males, current smokers, and persons with: heart disease, diabetes, stroke, higher cystatin c, and higher CRP." (PMID 36284701, 2022). "In studies evaluating DFU and osteomyelitis in people with diabetes, it was observed that CRP above 35 mg/L had a sensitivity of 80% and specificity of 89% for the presence of diabetic foot infection." (PMID 35450383, 2022).
diabetes (continued). "For venular tortuosity, associations with cardiometabolic risk factor differed by diabetes status: p values for interactions were statistically significant for TFMI, HbA1c, CRP, WCC and granulocyte count with adjustment." (PMID 35852586, 2022). "Infections of the respiratory, gastrointestinal, and urinary tract systems as well as cardiovascular diseases and diabetes are common in older adults and can trigger chronic low-grade inflammation (i.e., high CRP levels)." (PMID 36550123, 2022). "Morys (2021) found that BMI was positively related to higher plasma C-reactive protein, dyslipidemia, hypertension, and diabetes." (PMID 35682215, 2022). "In multivariate logistic regression models with SHR >1.14 as the dependent variable, log IL-10, IL-10/TNF-α ratio, log CXCL10, and log IFN-γ were separately included together with age, sex, presence of diabetes, CRP, and severity of disease as covariates." (PMID 36059840, 2022). "HR (95%CIs) for all-cause and cause-specific mortality according to serum 25 (OH)D, Cadmium and CRP among participants with diabetes." (PMID 35571939, 2022). "There were significant differences between groups for age, sex, C-reactive protein, lymphocyte count, albumin, diabetes, computed tomography findings, mean PNI, and PNI distribution." (PMID 35479742, 2022). "Risk factors associated with disease severity included older age, hypertension, cancer, diabetes mellitus (DM), obesity, cerebrovascular disease, chronic kidney disease, and elevated ferritin, D-dimer, and C-reactive protein (CRP) levels." (PMID 36505104, 2022). "Upon admission, elevated CRP, ferritin, and diabetes were independent predictors of mortality, as were persistently high CRP, neutrophilia, and the requirement of invasive mechanical ventilation during hospital stay." (PMID 35453779, 2022). "Concomitantly, the resolution of periodontal infection in individuals with diabetes and periodontitis has shown a significant reduction in high-sensitive C-reactive protein (hs-CRP) levels." (PMID 36289786, 2022). "Further intervention studies such as the AT1 receptor antagonist should be performed to accept CRP as a predictor of diabetes and cardiovascular disease." (PMID 35178206, 2022). "Multivariate regression analysis showed that the hs-CRP level and duration of diabetes most strongly influenced baPWV." (PMID 33628837, 2021). "Another retrospective study reported that patients with severe COVID-19 disease and diabetes had increased leucocytes, neutrophils count, and increased C-reactive protein (CRP), D-dimers, fibrinogen levels." (PMID 33788884, 2021). "Spearman's correlation showed that serum melatonin levels were negatively correlated with age (r = −0.159, P = 0.012), BMI, diabetes duration, HbA1c, hs-CRP, whereas positively correlated with HDL-C." (PMID 34007273, 2021). "When testing the superiority of apoB/apoA1 over apoB alone, they found that the difference was not statistically significant when adjusting for risk factors, such as obesity, smoking, dyslipidemia, hypertension, diabetes, and high C-reactive protein (CRP)." (PMID 34677405, 2021). "In “large neck” patients, a statistically significant higher prevalence of arterial hypertension (63 vs. 48%), diabetes (33 vs. 19%), obesity (26 vs. 14%), and high CRP levels (98 vs. 88%) was found." (PMID 34940406, 2021). "Diabetes is considered to be one of the underlying causes of the elevation of leukocyte count, NLR, and infection-associated markers, such as LDH, CRP, and ESR, which cause chronic low-grade inflammation." (PMID 33746672, 2021). "There were significant differences in age, hypertension, diabetes, dyspnea, white blood cell counts, lymphocyte counts, lactate dehydrogenase levels and CRP levels between the groups." (PMID 33390795, 2021). "Male gender, diabetes, higher C-reactive protein, and increased lactate dehydrogenase were the leading factors positively associated with elevated AST levels." (PMID 34179034, 2021).
diabetes (continued). "Higher urinary level of MA, age, CRP, lower level of serum albumin, eGFR ABI, diabetes, cerebral infarction, and CHD were also associated with CCVD, and statin reduced CCVD in Cox multivariate analysis (p<0.05)." (PMID 34707745, 2021). "There was statistically significant variation in age, gender, obesity, current smoking, hypertension, diabetes, dyslipidemia, hs-CRP and LVEF lipid parameters." (PMID 33845772, 2021). "As for CVS risk factors, the correlation of IMT with CVS risk factors such as hypertension, diabetes, erythrocyte sedimentation rate (ESR), c-reactive protein (CRP), and hyperlipidemia was found to be significant in all nine studies." (PMID 34513433, 2021). "Age; male sex; presence of hypertension, diabetes, and hypercholesterolemia; BMI value and levels of triglycerides, HDL-cholesterol, ALT, and hs-CRP were significantly associated with low muscle mass (p < 0.05)." (PMID 34440592, 2021). "This predictive value of ET-1 for incident CKD stage 3 or higher in women was borderline significant (p = 0.06) after adjustments for age, body mass index (BMI), exercise, smoking, alcohol, hypertension, diabetes, high-sensitive CRP and LDL-cholesterol." (PMID 34600499, 2021). "Independent factors on admission for mortality in SCAP patients with T2DM were increased numbers of comorbidities and diabetes-related complications; elevated CRP, NLR, BNP and blood lactate; as well as decreased blood pressure." (PMID 34876193, 2021). "This association remained statistically significant after adjustment for potential confounding factors (including age, sex, systolic blood pressure, total cholesterol, use of lipid-lowering drugs, diabetes, current smoking, chronic heart failure, hs-CRP)." (PMID 34896941, 2021). "Statistical models were fully adjusted for several factors, including age, sex, hypertension, diabetes, chronic lung disease, lymphocyte and platelet counts, aspartate aminotransferase, total bilirubin, albumin, creatine, C-reactive protein and D-dimer levels." (PMID 34025575, 2021). "CRP, neopterin and lactoferrin were higher among individuals with diabetes, also when adjusting for age, sex, and body mass index." (PMID 34341370, 2021). "Despite being nonsignificant, there was a trend towards increased mortality in patient with diabetes, D-dimer levels >1000 ugFEU/L, higher ferritin and prokalsitonin levels, an increased CRP/albumin ratio, and a lower neutrophil/lymphocyte ratio." (PMID 32950045, 2021). "In diabetes and obesity, increased levels of IL-6 and TNF-α have been demonstrated, whereas the serum levels of IL-6 and CRP have been shown to predict the future occurrence of diabetes mellitus type 2." (PMID 34452136, 2021). "An elevated CRP level is the marker of diabetes mellitus, insulin resistance, and cardiovascular disease." (PMID 34452136, 2021). "Insulin resistance is a central feature in the natural history of type 2 diabetes mellitus, of which CRP play a crucial role." (PMID 33676486, 2021). "Higher systemic CRP concentrations indicated increased risks of cardiovascular morbidity, diabetes, and metabolic syndrome more pronounced in women than in men." (PMID 32827080, 2021). "In our cohort, in the present study, patients with a “large neck” phenotype had a statistically significant higher prevalence of arterial hypertension, diabetes, obesity, and high CRP levels." (PMID 34940406, 2021). "In the analysis according to odds ratio, age, diabetes mellitus, CRP, eGFR, and BNP were related to low iron levels." (PMID 33504934, 2021). "Age, diabetes mellitus, coronary artery disease, atrial fibrillation, chronic kidney disease, C-reactive protein, statin therapy, chronic obstructive pulmonary disease, arterial hypertension and ED-A+ Fn were entered into the analysis as independent variables." (PMID 34207881, 2021). "Inflammation markers such as c-reactive protein (CRP) and IL-6 are involved in insulin resistance, which positively correlates with the progress of diabetes." (PMID 34539410, 2021).